OR8D1 (olfactory receptor family 8 subfamily D member 1)
Description:
Odorant receptor (Potential). May be involved in taste perception.
Synonyms: OR8D3; OST004; JCG9; PDJ9J14
Tractability: Antibody: its Gene Ontology location is reachable by antibodies, with high confidence; UniProt places it where antibodies can reach, with medium confidence; UniProt predicts a signal peptide or a membrane-spanning region.
Gene: Protein-coding gene on chromosome 11 (124,302,831 to 124,315,099, reverse strand). Ensembl gene ENSG00000196341.
Subcellular location: Cell membrane
Pathways (Reactome):
Sensory Perception: Expression and translocation of olfactory receptors; Olfactory Signaling Pathway
Gene Ontology:
Molecular function: olfactory receptor activity; G protein-coupled receptor activity
Biological process: G protein-coupled receptor signaling pathway; sensory perception of smell; detection of chemical stimulus involved in sensory perception of smell
Cellular component: plasma membrane; membrane
Genetic constraint (gnomAD): Missense variants: 382 observed, 371.6 expected, observed/expected ratio (o/e) 1.03, 90% interval 0.94 to 1.12. Synonymous variants: 143 observed, 148.77 expected, observed/expected ratio (o/e) 0.96, 90% interval 0.84 to 1.1.
Homologues: Orthologues: chimpanzee OR8D1 (99% identical), macaque OR8D1 (95% identical), pig OR8D1 (88% identical), dog OR8D1 (87% identical), mouse Or8d1 (85% identical), mouse Or8d1b (85% identical), rat Olr1271 (81% identical), mouse Or8d23 (79% identical), tropical clawed frog or5dd2b (48% identical). Paralogues in human: OR8D2 (70% identical), OR8D4 (65% identical), OR8G1 (64% identical), OR8A1 (63% identical), OR8G3 (62% identical), OR8G5 (62% identical), OR8B8 (61% identical), OR8B3 (59% identical), OR8B2 (59% identical), OR8G2P (58% identical), OR8B12 (57% identical), OR8B4 (57% identical), and 84 more.
Diseases named in the same sentence as OR8D1 in open-access papers:
OR8D1 is named in the same sentence as 2 diseases in open-access papers, as found by Europe PMC text mining. Sharing a sentence is not in itself a finding about the gene and the disease. The quoted sentences say what the papers report.
head and neck squamous cell carcinoma (1 paper, 2021). A squamous cell carcinoma that arises from any of the following anatomic sites: lip and oral cavity, nasal cavity, paranasal sinuses, pharynx, larynx, and salivary glands. "The top-ranked somatic eQTL genes with truncations include OR8D1 in LUSC, SOX10 in head and neck squamous cell carcinoma (HNSC), and PSG7 in kidney renal clear cell carcinoma (KIRC)." (PMID 33691015, 2021).
OR8D1 also shares sentences with these, for which no sentence is quoted: infection (1 paper).